ENSG00000277671
Gene: Miscellaneous RNA gene on chromosome 21 (8,250,060 to 8,250,149, forward strand). Ensembl gene ENSG00000277671.
Gene Ontology:
Biological process: chromatin remodeling